TNF (tumor necrosis factor)
Diseases named in the same sentence as TNF in open-access papers (continued):
Sharing a sentence is not in itself a finding about the gene and the disease.
cardiac hypertrophy (181 papers, 2009 to 2026). "STAT-3, a downstream target of IL-6, is implicated in cardiac hypertrophy, while tumor necrosis factor (TNF)-α has been observed to reduce ejection fraction and induce HF in animal studies." (PMID 39767820, 2024). "In DCM, TNF‐α was overexpression in the heart and caused myocardial fibrosis, myocardial hypertrophy, and IR." (PMID 38617433, 2024). "Activation of the TLRs pathway induces the translocation of NF-κB to the nucleus, where it promotes transcription of inflammation mediators, including IFN-γ, IL-6, and TNF-α, all of which are associated with cardiac hypertrophy." (PMID 37958859, 2023). "Previous studies have shown that proinflammatory cytokines, such as TNF-α, IL-1β, and IL-6, are closely associated with myocardial fibrosis, pathological cardiac remodeling, and myocardial hypertrophy." (PMID 38158445, 2023). "Previous studies reported that inflammatory factor, such as TNF-α and IL-6, cause cardiac hypertrophy and fibrosis through regulate the cardiac inflammatory response." (PMID 36471367, 2022). "Inflammation is also a hallmark of cardiac hypertrophy and involves factors such as interleukin (IL)-1β or tumor necrosis factor-alpha (TNF-α)." (PMID 33776771, 2021). "Over the past two decades, many studied have indicated that IL-1β, IL-6, and TNF-α are closely implicated in cardiac fibrosis, pathological cardiac remodeling, and cardiac hypertrophy." (PMID 34194329, 2021). "Under either pressure or volume overload model, upregulated TNF-α expression has been associated with cardiac hypertrophy, especially in pressure overload-induced hypertrophy." (PMID 33324685, 2020). "In contrast, TNF-α-deficient mice subjected to pressure overload were protected against cardiac hypertrophy, fibrosis and dysfunction." (PMID 30177883, 2018). "The cardiac mast cell induces MMP activation due to oxidative stress as well as TNF-α which causes degradation of collagen causing cardiac fibrosis in cardiac hypertrophy." (PMID 28066255, 2016). "Cardiac overexpression of TNF-α has been associated with cardiac hypertrophy and fibrosis, as well with left ventricular dysfunction." (PMID 25077824, 2014). "TNF‐α in the heart caused cell apoptosis, myocardial hypertrophy, and myocardial fibrosis." (PMID 38617433, 2024). "This suggests that the synergistic effect of SE and harmine against cardiac hypertrophy may be associated with the regulation of the TNF signalling pathway." (PMID 39351650, 2024). "Changes in inflammatory markers (such as C-reactive protein (CRP), interleukin-6 (IL-6), and tumor necrosis factor-α (TNF-α)) are associated with long sleep duration, which may contribute to ventricular hypertrophy." (PMID 38131034, 2023). "Many studies over the last two decades have shown that IL-1β, IL-6, and TNF-α are intimately linked to cardiac fibrosis, pathological cardiac remodeling, and cardiac hypertrophy, and the inflammatory cytokines induced following the activation of the nuclear factor-κB (NF-κB) pathway." (PMID 36164390, 2022). "Furthermore, TLR4 mediates Ang II-induced cardiac hypertrophy and is associated with myocardial TNF-α and IL-1β levels and NF-κB activity." (PMID 36247184, 2022). "Additionally, the upregulation of NF-κB—together with the excessive expression of pro-inflammatory cytokines such as interleukin-6 (IL-6) and tumor necrosis factor-alpha (TNF-α)—associated with cardiac hypertrophy has been observed in L-NAME hypertensive rats." (PMID 33801631, 2021). "TNF-α deficiency blunted pressure overload-induced cardiac hypertrophy." (PMID 34368120, 2021). "Increased TNF-α expression was associated with cardiac hypertrophy." (PMID 34368120, 2021). "Inflammatory cytokines have also been linked to the development of cardiac hypertrophy and fructose exposure in vitro increases the production of tumor necrosis factor (TNF)-α, interleukin (IL)-1β, IL-6 and transforming growth factor (TGF)-β1 in cardiomyocytes." (PMID 34267663, 2021).
cardiac hypertrophy (continued). "In our study, cardiac hypertrophy was associated with increased TNF-α and cardiac NF-κB expression." (PMID 29138670, 2017). "CTSB is upregulated in cardiomyocytes and stimulates the aortic banding-induced activation of TNF-α and cytochrome c release, thereby enhancing pressure overload-induced cardiac hypertrophy and fibrosis." (PMID 41277866, 2026). "Infiltrated macrophages in the heart can release proinflammatory cytokines, including tumor necrosis factor-α (TNF-α), IL-1β, and IL-6, which contribute to cardiac hypertrophy." (PMID 40141195, 2025). "Astragalus polysaccharides (APS) reduce ISO-induced myocardial hypertrophy by regulating energy biogenesis mediated by the TNF-α/PGC-1α signaling pathway." (PMID 39165261, 2024). "In response to pressure overload‐induced cardiac hypertrophy, TNFα is upregulated in the adult heart." (PMID 39351650, 2024). "By 6 months of age, SHRs continue to haveelevated blood pressure and exhibit increased myocardial hypertrophy, fibrosis,and inflammation, along with elevated levels of IL-6, IL-1β,TNF-α, and TGF-β1." (PMID 39076555, 2024). "Previous studies have shown that TNF contributes to adverse LV remodeling and dysfunction during cardiac pressure overload, and that transgenic mice overexpressing TNF specifically in the heart develop cardiac hypertrophy." (PMID 37296659, 2023). "Our results showed that the expression of RIPK1 and the phosphorylation of MLKL were significantly up-regulated in the myocardium of WT mice with myocardial hypertrophy, and the levels of serum IL-6 and TNF-α were increased." (PMID 37833985, 2023). "Cardiac hypertrophy occurs during the process of tissue repair and adaptation, in which some inflammatory markers can directly influence the increase in cardiac mass, for instance, TNFα binds to its receptor 1 and induces cardiac hypertrophy." (PMID 38137440, 2023). "In Ang II-induced hypertension rats, a blockade of TLR4 delayed the progression of hypertension and reduced the TNF-α and IL-1β levels and NF-κB activity in myocardial tissue, which improved cardiac hypertrophy." (PMID 36247184, 2022). "The expression and activation of pro-inflammatory cytokines, such as IL-1β, IL-6, IL-8, and TNF-α are involved in myocardial fibrosis, myocardial hypertrophy, oxidative stress-related injury, and cardiac dysfunction." (PMID 34997266, 2022). "In the development of cardiac hypertrophy, the increased expression of IL-6, TNF-α, and IL-1β is closely related to Collagen I and Collagen III deposition." (PMID 36270989, 2022). "For example, leptin treatment of cardiomyocytes from humans and neonatal rats has been found to induce TNF-α-/IL-6-mediated redox stress and cardiac hypertrophy." (PMID 36684585, 2022). "A clinical study found that, after non-surgical septal reduction therapy for patients with hypertrophic obstructive cardiomyopathy, the expression of tumor necrosis factor-α was decreased and cardiac hypertrophy was regressed." (PMID 35990977, 2022). "The results of the present study revealed that expression of RIPK1 and phosphorylation of MLKL were significantly upregulated in the myocardium of WT myocardial hypertrophy mice, and the levels of serum IL-6 and TNF-α were increased." (PMID 36046685, 2022). "Astragalus polysaccharide attenuates iso-induced cardiac hypertrophy through regulating tumor necrosis factor-α (TNF-α)/PGC1α signaling, resulting in decreased FFA contents." (PMID 35281941, 2022). "It is well known that the level of ANP indicates changes in cardiac hypertrophy, and the levels of TNF-α, IL-6 and fibrin indicate myocardial inflammation and fibrosis induced by cardiac hypertrophy." (PMID 35249458, 2022).
cardiac hypertrophy (continued). "In an ischemia/reperfusion-induced myocardial injury model, systemic or intracoronary injection of FSTL1 reduced the expression of inflammatory cytokines such as TNF-α and IL-6, thereby improving cardiac hypertrophy and dysfunction." (PMID 33936382, 2021). "Pathways that were previously associated with cardiac hypertrophy and cardiac remodeling (e.g. JAK-STAT, MAPK, estrogen, and TNF signaling pathways, and ECM-receptor interaction) were significantly upregulated in heart 6 and 24 hr after an MI." (PMID 33972017, 2021). "Many pro-inflammatory factors are involved in pressure overload-induced cardiac hypertrophy in mice, including IL-1β, IL-6, IL-18, and TNF-α." (PMID 34168567, 2021). "Overload pressure, oxidative stress and tissue injury, as well as the influence of neurohormonal and inflammatory mediators, like AngII, endothelin-1, catecholamines, growth factors and TNF-α, promote ventricular hypertrophy." (PMID 34489711, 2021). "The nucleoside counteracts the activity of many neurohumoral factors involved in cardiac hypertrophy, namely endothelin-1, renin-angiotensin-aldosterone system and TNF-α, and noradrenaline release from sympathetic nerves." (PMID 34489711, 2021). "For example, cardiac overexpression of TNF-α in mice induces cardiac hypertrophy and reduces contractility, whereas ablation of TNF-α attenuates cardiac hypertrophy, inflammation, apoptosis and fibrosis following aortic constriction." (PMID 33192505, 2020). "It is well documented that the expansion of TNF-α during heart disease especially cardiac hypertrophy via activation of inflammatory pathway and apoptotic along with the suppression of mitochondrial electron transport chain complexes." (PMID 32762480, 2020). "Angiotensin II infusion induced cardiomyopathy in db/db mice, manifested by cardiac hypertrophy, myocardial fibrosis and inflammation (TNFα, TLR4)." (PMID 31924211, 2020). "The results showed that LCZ696 significantly improved heart dysfunction, cardiac hypertrophy, and fibrosis and inhibited the expression of proinflammatory factors IL-6, IL-1β, and TNF-α in the circulating blood and heart tissues of mice." (PMID 32420365, 2020). "Transgenic mice with cardiac-specific overexpression of TNF-α developed dilated cardiomyopathy with ventricular hypertrophy, ventricular dilatation, interstitial infiltrates, interstitial fibrosis, and reduced ejection fraction." (PMID 33238643, 2020). "It has been reported that sUA increases tumor necrosis factor-alpha, stimulates mitogen-activated protein kinases, and activates the renin–angiotensin system, all of which are known to promote cardiac hypertrophy." (PMID 33324684, 2020). "It has been shown that induction of cardiac hypertrophy by AngII, Tumor necrosis factor -α and α-adrenergic stimuli is ROS-dependent." (PMID 31968660, 2020). "For example, some inflammatory cytokines such as TNF-α, IL-1β, and IL-6 directly induce cardiac hypertrophy and correlated with the severity of hypertrophy." (PMID 33324685, 2020). "TNF-α, mainly generated by activated macrophages, is a ubiquitous inflammatory cytokine that regulates the pathological process of cardiac hypertrophy." (PMID 33324685, 2020). "A previous study found that global knockout of TNF-α ameliorates pressure overload-induced cardiac hypertrophy and cardiac dysfunction." (PMID 33324685, 2020). "In the present study, we have observed enhanced expression of inflammatory genes such as TNF-α, IL-6, and IL-1β in hypertrophy heart." (PMID 32082481, 2020). "MAPKs not only regulate TNFα expression by several mechanisms, but also involved in different facets of cardiac hypertrophy, cardioprotection vs. myocardial cell death or cardiac remodeling." (PMID 33330645, 2020). "TNF-α inhibits cardiac contractility; provokes myocardial hypertrophy, ventricular remodeling, and cardiac fibrosis; and induces cardiomyocyte apoptosis." (PMID 33270628, 2020).
cardiac hypertrophy (continued). "Suppressing TNF-α converting enzyme by TNF-α Protease Inhibitor-1 (TAPI-1) to increase endogenous tmTNF-α expression significantly alleviated TAC-induced cardiac hypertrophy." (PMID 33270628, 2020). "TNF-α is an extremely important molecule used in cell proliferation, differentiation, growth and metabolism, which is closely related to the occurrence of cardiac hypertrophy." (PMID 31180540, 2019). "Individuals with CCC have high production of inflammatory mediators such as IFN-γ, TNF-α, IL-1β and nitric oxide (NO) which are involved with myocarditis, fibrosis, and myocardial hypertrophy." (PMID 30044791, 2018). "Cyclophosphamide (CTX) induces myocardial fibrosis and cardiac hypertrophy, as well as changes in the expressions of several cytokines, such as interleukin (IL)-2, IL-10, IL-6, and TNF-α, which can further facilitate the occurrence and development of AF." (PMID 30386232, 2018). "The greater diameter of cardiomyocytes indicated leftventricular hypertrophy and the highest levels of TNF-α were found at 4Wdeclining in 8W while fibrosis was more intense in 8W." (PMID 29738042, 2018). "Patients with CCC have high production of inflammatory cytokines such as IFN-γ, TNF-α, IL-1β and nitric oxide (NO) which are involved with myocarditis, fibrosis and myocardial hypertrophy." (PMID 30044791, 2018). "In the failing heart, TNF contributes to the contractile dysfunction, provokes heart hypertrophy, and induces apoptosis of cardiac myocytes." (PMID 29895751, 2018). "TNF-α has been reported to exert a crucial role in the development of myocardial hypertrophy and dysfunction." (PMID 29138670, 2017). "First, it has been reported that SUA increases tumor necrosis factor-alpha, stimulates mitogen-activated protein kinases, and activates the renin-angiotensin system, all of which are known to promote cardiac hypertrophy." (PMID 27054027, 2016). "Studies, in fact, show that TNF-α induces apoptosis in cardiomyocytes, suppresses cardiac contractility, and provokes myocardial hypertrophy." (PMID 26665009, 2015). "In our study, a marked attenuation of Ang II-induced cardiac hypertrophy and fibrosis was demonstrated in TNF-α-/- mice, as indicated by decreased profibrotic gene expression and decreased interstitial and perivascular fibrosis in the cardiac tissue." (PMID 26378790, 2015). "Chronic Ang II infusion significantly increased mean arterial pressure and cardiac hypertrophy in WT mice, while, TNF-α inhibition with etanercept resulted in attenuated Ang II-induced hypertensive and cardiac hypertrophic responses." (PMID 26378790, 2015). "Our previous study revealed a direct effect of TNF-α on cardiac hypertrophy in cultured cardiomyocytes." (PMID 24521405, 2014). "In the myocardial ischemia process, TNF-α can inhibit myocardial contraction, promote myocardial hypertrophy, and induce apoptosis of cardiac cells." (PMID 24817898, 2014). "Hydrogen peroxide directly induced cardiac hypertrophy, and antioxidants prevent hypertrophy induced by tumor necrosis factor-α and angiotensin II." (PMID 25247053, 2014). "The RT protocol was able to attenuate cardiac hypertrophy, left ventricular collagen volume fraction and reduced IL-6 and the ratio of TNF-α/IL-10; also, there was increased IL-10 in CHF rats." (PMID 25340545, 2014). "Chronic hypertension causes cardiac hypertrophy, characterized by low-grade inflammation and accompanied by increased expression and activity of TLR4, and elevated gene expression of TNF-α and IL-6 in cardiac tissue." (PMID 24223475, 2013). "An inhibition of ventricular hypertrophy by blocking MMP activity was earlier seen in the TNF-α transgenic mouse model of dilated cardiomyopathy." (PMID 24116115, 2013). "TNF-mediated eccentric cardiac hypertrophy in response to intermittent hypoxia was shown to be mediated by ERK and STAT3 activation in adult rat myocardium." (PMID 23365487, 2013).
cardiac hypertrophy (continued). "Chronic Ang II infusion resulted in a significant increase in MAP and cardiac hypertrophy, which was attenuated by inhibition of brain TNF with etanercept." (PMID 23691105, 2013). "Second, transgenic mice with overexpressing cardiac TNF-α would first develop myocardial hypertrophy with preserved systolic function." (PMID 23675418, 2013). "In concordance, TNFα-overexpressing mice with cardiac hypertrophy and TNFα-induced hypertrophic cardiomyocytes showed reduction of PPARγ coactivator-1α expression and its targets (PPAR isoforms)." (PMID 21772665, 2011). "Significantly increased TNF-α expression is found in cardiac hypertrophy induced in stretched myocytes and in hemodynamic-over-loaded myocardium." (PMID 19210763, 2009). "CA may attenuate cardiac inflammation and myocardial hypertrophy in the RH model through the TNF and IL-17 signaling pathways." (PMID 39337549, 2024). "TNF‐α mediates NF‐κB activity, thereby inducing cardiac hypertrophy." (PMID 39351650, 2024). "On the other hand, TNF-α, a pro-inflammatory cytokine known to induce cardiac hypertrophy, fibrosis, dysfunction under pressure overload, and chronic heart injuries, may trigger the activation of NLRP3 through the elevation of ROS levels." (PMID 37958859, 2023). "Additionally, in this experimental model, an increase in systemic oxidative stress, alterations in cardiomyocytes, such as lower LV vascularization, cardiac hypertrophy, and higher TNF-α expression, were observed." (PMID 37585913, 2023). "The results showed that PI3K and TNF were downregulated in cardiac hypertrophy." (PMID 35433687, 2022). "Our group highlighted a TNFα/TNFR2-dependent signaling leading to ORAI3-dependent Ca2+ channel activation promoting early adaptive cardiac hypertrophy (ECH) and resistance to oxidative stress in rats subjected to isoproterenol infusion or abdominal aortic banding." (PMID 35406812, 2022). "Proinflammatory cytokines, including IL-6, IL-1β, IFN-γ, IL-17, and TNF-α, could induce cardiac hypertrophy, fibrosis, and apoptosis and further induce inflammation, ultimately resulting in HF." (PMID 35669500, 2022). "If ASOs or other small molecular inhibitors are designed for the combination of MBNL1/Myocardin and MBNL1/TNF‐α, it may be possible to inhibit cardiac hypertrophy and prevent the apoptosis of cardiomyocytes." (PMID 33295096, 2021). "Moreover, administration of anti‐TNF‐α agents in diabetic rats significantly decreased urinary TNF‐α concentrations and prevented renal hypertrophy." (PMID 33634991, 2021). "Etanercept, a TNF-α inhibitor, has been shown to alleviate cardiac hypertrophy." (PMID 33916242, 2021). "As chemokines are secondary cytokines induced by pro-inflammatory cytokines including IL-1 and TNF-α, the positive correlation between cardiac hypertrophy and eotaxin/MIP-1α in aging males may reflect higher levels of IL-1 and TNF-α." (PMID 32857156, 2021). "However, Ginsenoside Rg1, a traditional Chinese medicine, was found to downregulate TNF-α expression, both at mRNA and protein levels, in a concentration-dependent manner in rat hearts following pressure overload-induced cardiac hypertrophy." (PMID 33324685, 2020). "Moreover, Akt activation promotes TNF-α-induced elevation in mRNA levels of IL-6, IL-1α, and IL-1β in cardiac fibroblasts and cardiac hypertrophy in primary cardiomyocytes." (PMID 32831633, 2020). "ERK1/2 activation mediates gp130-induced cardiac hypertrophy and PE-induced TNF-α production." (PMID 32831633, 2020). "Also, cardiac hypertrophy was attenuated in TNF-α−/− mice and the therapy with recombinant TNF restored all responses induced by Ang II in WT." (PMID 31321561, 2019). "In mice, cardiomyocyte-specific overexpression of TNF-α induced dilated cardiomyopathy characterized by ventricular hypertrophy and dilatation, myocardial infiltration of inflammatory cells, fibrosis and cardiomyocyte apoptosis, together with reduced ejection fraction." (PMID 30177883, 2018).